ZNF410 (zinc finger protein 410)
Description:
Transcription factor that binds to the sequence motif 5'-CATCCCATAATA-3', and is specifically required to silence expression of fetal hemoglobin in adult erythroid cells. Prevents expression of fetal hemoglobin genes HBG1 and HBG2 through CHD4: acts as a direct transcriptional activator of CHD4, a central component of the NuRD complex that represses transcription of fetal hemoglobin genes HBG1 and HBG2 in erythroid cells. May also activate transcription of matrix-remodeling genes such as MMP1 during fibroblast senescence. May activate transcription of the gap junction gene GJC1, perhaps in response to increasing glucose. However, recent studies suggest that ZNF410 is dedicated to regulate expression of a single gene: CHD4.
Synonyms: APA1; APA-1
Tractability: PROTAC: UniProt records ubiquitination sites on it; ubiquitination databases record sites on it.
Gene: Protein-coding gene on chromosome 14 (73,886,201 to 73,932,521, forward strand). Ensembl gene ENSG00000119725.
Subcellular location: Nucleus; Chromosome
Subcellular location (Human Protein Atlas): Nucleoplasm; Cytosol
Gene Ontology:
Molecular function: DNA-binding transcription factor activity; protein binding; RNA polymerase II cis-regulatory region sequence-specific DNA binding; sequence-specific double-stranded DNA binding; transcription coregulator activity; sequence-specific DNA binding
Biological process: negative regulation of gene expression; positive regulation of transcription by RNA polymerase II; regulation of transcription by RNA polymerase II; positive regulation of DNA-templated transcription
Cellular component: chromosome; nucleoplasm; nuclear lumen; nucleus
Genetic constraint (gnomAD): Loss-of-function variants: 18 observed, 56.57 expected, observed/expected ratio (o/e) 0.32, 90% interval 0.22 to 0.47. The upper end of that interval is the gene's LOEUF score, 0.47, which puts it in group 2 of 6, group 1 being the genes least tolerant of losing a copy. Missense variants: 405 observed, 600.75 expected, observed/expected ratio (o/e) 0.67, 90% interval 0.62 to 0.73. Synonymous variants: 191 observed, 220.26 expected, observed/expected ratio (o/e) 0.87, 90% interval 0.77 to 0.98.
Homologues: Orthologues: chimpanzee ZNF410 (97% identical), macaque ZNF410 (97% identical), guinea pig ZNF410 (96% identical), rabbit ZNF410 (95% identical), dog ZNF410 (95% identical), rat Zfp410 (94% identical), mouse Zfp410 (94% identical), pig ZNF410 (94% identical), tropical clawed frog znf410 (54% identical), zebrafish znf410 (45% identical). Paralogues in human: PRDM10 (23% identical), HIC1 (18% identical), PRDM1 (18% identical), ZNF143 (18% identical), ZNF76 (18% identical), MTF1 (17% identical), ZBTB16 (17% identical), HIC2 (16% identical), ZBTB7C (16% identical), SNAI3 (15% identical), ZNF276 (14% identical), ZNF653 (14% identical), and 24 more.
Diseases named in the same sentence as ZNF410 in open-access papers:
ZNF410 is named in the same sentence as 49 diseases in open-access papers, as found by Europe PMC text mining. Sharing a sentence is not in itself a finding about the gene and the disease. The quoted sentences say what the papers report.
breast carcinoma (10 papers, 2007 to 2024). "Thus, we selected 2 TF hubs (MDM4 and ZNF410) and 2 lncRNA hubs (AC084219 and CTB-89H12) with the highest degrees from the lncRNA-TF-associated ceRNA network and detected their expression in various subtypes of breast cancer." (PMID 32802855, 2020).
hemoglobinopathies (1 paper, 2021). "Targeting ZNF410 in erythroid cells led to CHD4 downregulation and HbF induction, without compromising erythroid cell differentiation, thus validating ZNF410 as a promising potential target for treating hemoglobinopathies." (PMID 34713248, 2021).
sickle cell disease (1 paper, 2023). Sickle cell anemias are chronic hemolytic diseases that may induce three types of acute accidents: severe anemia, severe bacterial infections, and ischemic vasoocclusive accidents (VOA) caused by sickle-shaped red blood cells obstructing small blood vessels and capillaries. "Overall, efforts from the last decades have shed enough light on the mechanisms that orchestrate hemoglobin switching for developing gene therapy approaches targeting such discovered regulators (e.g., BCL11A, ZNF410) for sickle cell disease and β-thalassemia." (PMID 36992422, 2023). "Sickle cell disease patient HSPCs that have been treated with a vector containing both a ZNF410 and a BCL11A shRNAmiRs and differentiated into erythrocytes led to an increase of 10% HbF and a significant decrease of sickled cells in comparison to BCL11A shRNAmiR only vector treated cells." (PMID 36992422, 2023). "Hence, the ZNF410 and BCL11A shRNAmiR vector shows a greater potential and application in both sickle cell disease and β-thalassemia therapy." (PMID 36992422, 2023).
cancer (6 papers, 2007 to 2024). A tumor composed of atypical neoplastic, often pleomorphic cells that invade other tissues. "Hub nodes such as MDM4, ZNF410, AC0842-19, and CTB-89H12 were differentially expressed between cancer and normal sample in different subtypes and tumor stages." (PMID 32802855, 2020).
ZNF410 also shares sentences with these, for which no sentence is quoted: cervical cancer (2 papers); COVID-19 (2); diabetes (2); melanoma (2); Obesity (2); ovarian carcinoma (2); prostate carcinoma (2); psoriasis (2); skin cancer (2); acute pancreatitis (1); alcohol (1); alcohol abuse (1); Alzheimer disease (1); asthma (1); atopic dermatitis (1); autism (1); autism spectrum disorder (1); chronic myeloid leukemia (1); cognitive decline (1); colorectal cancer (1); dengue (1); depression (1); diabetic nephropathy (1); hypovitaminosis D (1); leprosy (1); liver cancer (1); lung carcinoma (1); lymphoma (1); major depressive disorder (1); non-small cell lung carcinoma (1).
A further 15 diseases each share a sentence with ZNF410 in 1 paper.